SBNO1 (strawberry notch homolog 1)
Description:
Plays a crucial role in the regulation of neural stem cells (NSCs) proliferation. Enhances the phosphorylation of GSK3B through the PI3K-Akt signaling pathway, thereby upregulating the Wnt/beta-catenin signaling pathway and promoting the proliferation of NSCs. Improves ischemic stroke recovery while inhibiting neuroinflammation through small extracellular vesicles (sEVs)-mediated mechanism. Enhances the secretion of sEVs from NSCs, which in turn inhibit both the MAPK and NF-kappaB pathways in microglia. This inhibition suppresses the pro-inflammatory M1 polarization of microglia, promoting a shift towards the M2 anti-inflammatory phenotype, which is beneficial for reducing neuroinflammation.
Synonyms: MOP3; FLJ10701; FLJ10833; Sno
Tractability: PROTAC: ubiquitination databases record sites on it; its protein half-life has been measured.
Gene: Protein-coding gene on chromosome 12 (123,289,109 to 123,365,184, reverse strand). Ensembl gene ENSG00000139697.
Subcellular location: Nucleus
Subcellular location (Human Protein Atlas): Nucleoplasm
Gene Ontology:
Biological process: negative regulation of canonical NF-kappaB signal transduction; negative regulation of MAPK cascade; negative regulation of neuroinflammatory response; positive regulation of canonical Wnt signaling pathway; positive regulation of neural precursor cell proliferation; regulation of DNA-templated transcription; positive regulation of signal transduction
Cellular component: nucleus
Genetic constraint (gnomAD): Loss-of-function variants: 12 observed, 106.69 expected, observed/expected ratio (o/e) 0.11, 90% interval 0.071 to 0.18. The upper end of that interval is the gene's LOEUF score, 0.18, which puts it in group 1 of 6, group 1 being the genes least tolerant of losing a copy. Missense variants: 823 observed, 1,207.2 expected, observed/expected ratio (o/e) 0.68, 90% interval 0.64 to 0.72. Synonymous variants: 444 observed, 419.78 expected, observed/expected ratio (o/e) 1.06, 90% interval 0.98 to 1.14.
Homologues: Orthologues: chimpanzee SBNO1 (99% identical), macaque SBNO1 (99% identical), mouse Sbno1 (97% identical), rat Sbno1 (97% identical), guinea pig SBNO1 (97% identical), rabbit SBNO1 (95% identical), pig SBNO1 (95% identical), dog SBNO1 (91% identical), tropical clawed frog sbno1 (87% identical), zebrafish sbno1 (80% identical). Paralogues in human: SBNO2 (47% identical).
Diseases named in the same sentence as SBNO1 in open-access papers:
SBNO1 is named in the same sentence as 20 diseases in open-access papers, as found by Europe PMC text mining. Sharing a sentence is not in itself a finding about the gene and the disease. The quoted sentences say what the papers report.
schizophrenia (5 papers, 2020 to 2025). A major psychotic disorder characterized by abnormalities in the perception or expression of reality. "Sbno1 is a nuclear-localized transcriptional regulator important in Notch and Hippo signaling, which has been associated with schizophrenia and may be important for brain function." (PMID 32416732, 2020). "Other studies have suggested a link between schizophrenia and SBNO1." (PMID 39982356, 2025). "This conclusion, along with multiple studies linking SBNO1 to schizophrenia, may explain why schizophrenic patients have olfactory dysfunction." (PMID 39982356, 2025).
cholangiocarcinoma (1 paper, 2026). A carcinoma that arises from the intrahepatic biliary tree (intrahepatic cholangiocarcinoma) or from the junction, or adjacent to the junction, of the right and left hepatic ducts (hilar cholangiocarcinoma). "In hepatocellular carcinoma (HCC) and cholangiocarcinoma (CCA), SBNO1 protein was significantly increased and localized to the nucleus suggesting its involvement in gene regulation." (PMID 41649174, 2026).
Intellectual disability (1 paper, 2021). "SBNO1, the corresponding gene of rs7980687, is associated with intellectual disability." (PMID 33969932, 2021).
ischemic stroke (1 paper, 2024). A stroke disorder caused by obstruction of blood flow to the brain, due to thrombotic (local blood clot formation) or embolic (due to a blood clot or other material traveling from another site) event. "Here, we investigated the role and the mechanism of Sbno1 in NSCs development and the potential therapeutic value of Sbno1 in ischemic stroke." (PMID 39343943, 2024). "The results showed that during the process of ischemic stroke, with the M1 polarization of microglia and neuroinflammation, the number of cells double-positive for Sbno1 and the microglial marker IBA-1 continued to increase." (PMID 39343943, 2024). "To further verify whether Sbno1 has potential therapeutic effects on ischemic stroke, we conducted a series of in vivo experiments." (PMID 39343943, 2024). "Subsequently, through histological examination (HE and immunohistochemical staining), we confirmed that overexpressing of Sbno1 in the hippocampal region exhibited lower levels of neuroinflammation and a higher number of surviving neurons following ischemic stroke." (PMID 39343943, 2024).
liver cancer (1 paper, 2026). An epithelial or non-epithelial malignant neoplasm that arises from the liver. "Here, we found that Strawberry Notch 1 (SBNO1) is upregulated in several cancer entities and elucidated the role of SBNO1 in liver cancer development." (PMID 41649174, 2026). "Thus, we identified SBNO1 as a transcriptional regulator required for liver cancer development and progression." (PMID 41649174, 2026). "Deletion of Sbno1 in murine liver cancer cells Hep55.1C reduced tumor growth in vivo." (PMID 41649174, 2026).
metabolic syndrome (1 paper, 2023). A cluster of metabolic risk factors for CARDIOVASCULAR DISEASES and TYPE 2 DIABETES MELLITUS. "In addition, GWAS analyses in human metabolic syndrome discovered the association of the strawberry notch homolog 1 (SBNO1) gene on plasma high-density lipoprotein cholesterol concentration, whereas the vestigial like family member 2 (VGLL2) gene was linked to the fatty acids profile in sheep." (PMID 37141193, 2023).
Stroke (1 paper, 2024). Sudden impairment of blood flow to a part of the brain due to occlusion or rupture of an artery to the brain. "Furthermore, we conducted HE and immunofluorescence staining to examine the post-stroke brain’s pathological conditions and explore the underlying reasons for the enhanced post-stroke recovery in mice with hippocampal overexpression of Sbno1." (PMID 39343943, 2024). "Sbno1 also enhanced the tolerance of NSCs to ischemia and hypoxia, thereby improving their survival rate after stroke." (PMID 39343943, 2024). "The results showed that in the acute phase of stroke (72 h), there is a lower level of inflammatory cell infiltration in Sbno1-overexpressed mice compared with control mice." (PMID 39343943, 2024). "We found that the expression level of Sbno1 in neural stem cells was upregulated after stroke." (PMID 39343943, 2024). "Therefore, further investigate the reasons for the lower infiltration of inflammatory cells in the hippocampus of mice overexpressing Sbno1 after stroke, we conducted NTA and WB to identify sEV derived from NSCs." (PMID 39343943, 2024). "In addition, with overexpression of Sbno1 in the hippocampus, post-stroke behavioral scores were superior to the wild-type mice, and immunofluorescence staining revealed an increased number of newly generated neurons." (PMID 39343943, 2024). "For patients with disabilities following a stroke, gene therapy utilizing AAV carrying Sbno1 can upregulate the expression of Sbno1 in human hippocampal NSCs, thereby promoting the proliferation of endogenous NSCs and intrinsic repair." (PMID 39343943, 2024). "To further investigate the therapeutic effects of sEV, we administered Sbno1-NSCs-sEV, GFP-NSCs-sEV, or PBS (control) via stereotactic intracerebral injection to mice after stroke." (PMID 39343943, 2024).
type 2 diabetes (1 paper, 2022). "Two adjacent genes MPHOSPH9 and SBNO1, located in 12q24, were reported as having susceptible associations with type 2 diabetes." (PMID 36174000, 2022).
neurodevelopmental disorder (1 paper, 2025). A behavioral and cognitive disorder with onset during the developmental period that involves impaired or aberrant development of intellectual, motor, or social functions. "Human genome studies have suggested that strawberry notch homologue 1 (SBNO1) is crucial for normal brain development, with mutations potentially contributing to neurodevelopmental disorders." (PMID 39982356, 2025).
neurological diseases (1 paper, 2025). "Given that neuronal genome instability has been implicated in neurological diseases, dysfunction of a molecular network in which SBNO1 and YEATS4 are involved may contribute to disease pathogenesis." (PMID 40707437, 2025). "This study does not elucidate the mechanism of SBNO1 contributing to neurological diseases." (PMID 40707437, 2025).
tumor (1 paper, 2026). "Furthermore, Sbno1-deletion reduced biliary differentiation and angiogenesis in the tumor margin, underscoring the necessity of Sbno1 in Notch-driven CCA formation." (PMID 41649174, 2026).
SBNO1 also shares sentences with these, for which no sentence is quoted: cancer (2 papers); gastric cancer (1); hepatocellular carcinoma (1); hyperlipidemia (1); ischemia (1); Knee Osteoarthritis (1); lung carcinoma (1); microcephaly (1); Obesity (1).